GOLM2 (golgi membrane protein 2)
Synonyms: CASC4; H63; DKFZp459F1927
Tractability: Antibody: UniProt predicts a signal peptide or a membrane-spanning region. PROTAC: ubiquitination databases record sites on it.
Gene: Protein-coding gene on chromosome 15 (44,288,699 to 44,415,758, forward strand). Ensembl gene ENSG00000166734.
Subcellular location: Membrane
Subcellular location (Human Protein Atlas): Golgi apparatus
Gene Ontology:
Cellular component: Golgi apparatus; membrane
Genetic constraint (gnomAD): Loss-of-function variants: 12 observed, 30.39 expected, observed/expected ratio (o/e) 0.39, 90% interval 0.25 to 0.64. The upper end of that interval is the gene's LOEUF score, 0.64, which puts it in group 2 of 6, group 1 being the genes least tolerant of losing a copy. Missense variants: 370 observed, 416.73 expected, observed/expected ratio (o/e) 0.89, 90% interval 0.81 to 0.97. Synonymous variants: 134 observed, 159.47 expected, observed/expected ratio (o/e) 0.84, 90% interval 0.73 to 0.97.
Homologues: Orthologues: chimpanzee GOLM2 (99% identical), dog GOLM2 (91% identical), guinea pig GOLM2 (91% identical), mouse Golm2 (90% identical), pig GOLM2 (89% identical), rat Golm2 (89% identical), rabbit GOLM2 (89% identical), macaque GOLM2 (84% identical), tropical clawed frog golm2 (51% identical), zebrafish golm2 (49% identical). Paralogues in human: GOLM1 (24% identical).
Diseases named in the same sentence as GOLM2 in open-access papers:
GOLM2 is named in the same sentence as 11 diseases in open-access papers, as found by Europe PMC text mining. Sharing a sentence is not in itself a finding about the gene and the disease. The quoted sentences say what the papers report.
breast carcinoma (5 papers, 2018 to 2025). "SMOC1 plays essential roles in both eye and limb development, whereas GOLM2’s function is not well characterized but was associated with breast cancer and glioblastoma." (PMID 37047248, 2023).
cancer (10 papers, 2006 to 2025). A tumor composed of atypical neoplastic, often pleomorphic cells that invade other tissues. "One of the validated hits from the screen was the Cancer susceptibility candidate 4 (CASC4, also known as GOLM2) gene, which encodes a predicted Golgi-membrane protein." (PMID 38030811, 2024).
GOLM2 also shares sentences with these, for which no sentence is quoted: tumor (4 papers); triple-negative breast carcinoma (3); ovarian carcinoma (2); COVID-19 (1); glioblastoma (1); hepatocellular carcinoma (1); lung carcinoma (1); metastatic melanoma (1); serous carcinoma (1).